INS (insulin)
Diseases named in the same sentence as INS in open-access papers (continued):
Sharing a sentence is not in itself a finding about the gene and the disease.
type 2 diabetes (continued). "This is because care of type 2 diabetes warrants intense life-style adaptations, polypharmacy and insulin centered regimens." (PMID 25722966, 2015). "Adrenergic stimulation and plasma epinephrine release were proven to be major determinants of platelet activation in insulin-induced severe hypoglycemia in type 2 diabetes." (PMID 25928628, 2015). "In line with a potential positive effect of ghrelin on glucose homeostasis, fasting ghrelin is lower in obese insulin resistant adolescents with polycystic ovary syndrome and type 2 diabetic patients." (PMID 25723719, 2015). "The study investigated the impact of insulin glargine exposure on cardiovascular mortality in type 2 diabetes patients with incident insulin initiation." (PMID 26176017, 2015). "Exendin-4, a glucagon-like peptide-1 (GLP-1) receptor agonist is among those treatments of type 2 diabetes that lower blood glucose level by increasing glucose-dependent insulin secretion and suppressing excess glucagon secretion." (PMID 26546347, 2015). "Metformin treatment in type 2 diabetes in pregnancy required lower dose of add-on insulin, at a later gestational age for maintaining glycemic control when compared with insulin treatment." (PMID 25874236, 2015). "Genistein can be used not only to treat type 2 diabetes but also to stimulate insulin release in type 1 diabetes." (PMID 26393547, 2015). "This is a pilot study evaluating an approach to insulin titration using text messages and phone calls among patients with insulin-dependent type 2 diabetes in the outpatient medical clinic of Bellevue Hospital Center, a safety-net hospital in New York City." (PMID 25794243, 2015). "It is FDA approved for treating type 2 diabetes and improves glycemic control by augmenting insulin secretion from the pancreas." (PMID 26010091, 2015). "A 75-g oral glucose tolerance test was used to diagnose type 2 diabetes, and fasting and 2-h-postload glucose and insulin concentrations were measured." (PMID 26277879, 2015). "It is sometimes difficult to distinguish between type 1 diabetes and type 2 diabetes in patients with intensive insulin therapy." (PMID 25621692, 2015). "Development of type 2 diabetes (T2DM) is characterized by tissue resistance to insulin action and failure of pancreatic beta cells to secrete insulin to maintain glucose homeostasis." (PMID 26607656, 2015). "Type 1 and type 2 diabetes are complex diseases characterised by progressive failure of the insulin producing pancreatic β-cells." (PMID 25866760, 2015). "Neuronal pathways can produce an effect on insulin sensitivity, and contribute to insulin resistance syndrome components in humans, especially for type 2 diabetes and obesity." (PMID 26308950, 2015). "Type 2 diabetes (T2D) is a metabolic disorder characterized by high blood sugar levels due to increased insulin resistance, in which the body’s cells have lost the ability to respond adequately to relatively normal levels of insulin." (PMID 25880500, 2015). "IL-6 on the other hand suppresses the production of insulin in subjects with type II diabetes, which indicates increased insulin sensitivity." (PMID 25699273, 2015). "Glyburide is widely used in type 2 diabetes through its action on stimulating insulin release from the β-cells." (PMID 26176625, 2015). "The metabolism of proteins is abnormal in HFD-STZ induced type 2 diabetes due to enhanced insulin resistance and muscle wasting." (PMID 26783461, 2015). "The aim of this study was to investigate the relationship between serum 25-hydroxy vitamin D (25-OHD) and insulin sensitivity and β-cell function in newly diagnosed type 2 diabetes." (PMID 25741510, 2015). "There are only two studies to date that included an investigation of treatment satisfaction when adding insulin glargine versus NPH insulin to oral therapy in patients with type 2 diabetes." (PMID 26055391, 2015).
type 2 diabetes (continued). "We have demonstrated treatment of GK rats, an animal model of type 2 diabetes, with GP extract for two weeks significantly improved glucose tolerance, increased plasma insulin levels, and increased insulin secretion from islets isolated from the treated rats." (PMID 26199630, 2015). "Individuals born of low birth weight or SGA have been shown to have reduced insulin sensitivity and increased likelihood of developing type 2 diabetes." (PMID 25760717, 2015). "Remarkably, intraperitoneal injections of NAADP were found to restore glucose-evoked insulin secretion in the db/db mouse model of type-2 diabetes and to ameliorate blood glucose regulation." (PMID 26152717, 2015). "In a recent study, insulin was shown to suppress inflammatory pathway in obese individuals with type II diabetes." (PMID 26783384, 2015). "Other than the listed agents, insulin and analogues are used in the late stage of type 2 diabetes, especially in patients with poor glycemic control." (PMID 25866533, 2015). "As previously demonstrated in monkeys, a similar decrease in fasting C-peptide/insulin that precedes overt type 2 diabetes was seen in our dysmetabolic monkeys, and pioglitazone treatment significant increased this ratio." (PMID 25954816, 2015). "Recently, we provided evidence that Pio improved retinal insulin signaling in the BBZDR/Wor type 2 diabetes rat model in a PPARγ-dependent manner." (PMID 26336514, 2015). "Examples include the potential role of insulin signaling in type II diabetes, or that of the mitogen activated protein kinase (MAPK) signaling circuit in hypertension." (PMID 25774510, 2015). "Concurrency of hyperglycemia and hyperinsulinemia in type 2 diabetes, make insulin prone to be glycated." (PMID 26311627, 2015). "Insulin treatment is commonly used in patients with type 2 diabetes when lifestyle changes and oral hypoglycemic agents (OHA) fail to achieve adequate glycemic control." (PMID 28702235, 2015). "Combined DPP4 inhibitor and insulin therapy was introduced in Japan in 2013, and numerous patients with type 2 diabetes receiving insulin began to additionally receive DPP4 inhibitors." (PMID 25780477, 2015). "Insulin-stimulated glucose transport is important for the control of plasma glucose levels, and this process is severely disrupted in type 2 diabetes and other insulin-resistant states." (PMID 26083118, 2015). "Late stage type II diabetes can be effectively treated by a combination therapy of oral hypoglycemic drugs plus insulin." (PMID 26681965, 2015). "Cross-sectional relationships of lymphocyte subpopulations with type 2 diabetes (n = 154) and fasting glucose and insulin concentrations were evaluated by generalized linear models." (PMID 26458065, 2015). "The phosphorylated form of AHS acts as a natural competitve inhibitor of insulin, which blocks both activities, potentially contributing to the development of type-2 diabetes." (PMID 26441666, 2015). "Here, we demonstrated that RDX markedly improved insulin sensitivity and glucose metabolism by increasing glucose uptake in peripheral tissues of obese type 2 diabetic Otsuka Long-Evans Tokushima Fatty (OLETF) rats." (PMID 26450431, 2015). "GzmB increases inflammation in type 1 and type 2 diabetes and impairs insulin secretion from islet cells as part of the mechanism by which it kills pancreatic β cells in the development of type 1 diabetes." (PMID 26375667, 2015). "First- and second- phase insulin secretion are impaired in type 2 diabetes and under hyperglycemic glucose clamp conditions, endogenous GLP-1 is reported to augment both phases of insulin secretion in response to duodenal nutrition perfusion." (PMID 25811109, 2015). "In a series of 138 patients with DKA, type 1 diabetes patients were severely more acidotic, but type 2 diabetes patients required longer insulin infusion time." (PMID 26180779, 2015).
type 2 diabetes (continued). "Both deteriorated insulin sensitivity (SI) and impaired insulin secretion are recognized as 2 of the foremost forms of pathophysiology for type 2 diabetes (T2DM)." (PMID 25815010, 2015). "Type 2 diabetes (T2D) is where a relative beta cell insufficiency results from failure of compensatory upregulation of insulin production capacity in response to increasing peripheral insulin resistance." (PMID 26220792, 2015). "In this study, we aimed to show that few, preprandial glycemic readings are adequate to assess the glycemic control and variability in patients with type 2 diabetes, which were under insulin and vildagliptin treatment." (PMID 26587020, 2015). "Hepatic resistance to insulin is associated with NAFLD and is an important factor in the pathogenesis of type 2 diabetes and metabolic syndrome." (PMID 25875942, 2015). "We next tested P5 efficacy in the DIO mouse model of pre-type 2 diabetes (obese hyperglycaemic and insulin-resistant mice)." (PMID 26621478, 2015). "This randomized clinical study reports the results of metformin versus insulin treatment in women with type 2 diabetes in pregnancy." (PMID 25874236, 2015). "Type 2 diabetes is a complex metabolic disorder of insulin sensitivity and action on peripheral tissues like skeletal muscle and adipose tissue and of impaired insulin secretion." (PMID 26475130, 2015). "Eligible SPK candidates are defined as diabetic patients on insulin treatment with a C-peptide ≤ 2 ng/mL, or C-peptide ≥ 2 ng/mL and BMI < 28 kg/m2, to permit and define eligibility for type 2 diabetes candidates." (PMID 26239558, 2015). "The common causes of recurrent hypoglycemia during this period are congenital hyperinsulinism, inborn errors of carbohydrate, amino acid and lipid metabolism, and insulin therapy for type 1 and type 2 diabetes." (PMID 26343738, 2015). "Type 2 diabetes is the consequence of insufficient production or improper utilization of cellular insulin." (PMID 26703529, 2015). "Type 2 diabetes (T2D) is characterized by insulin resistance i.e., inability of tissues to respond to insulin, and a progressive pancreatic beta cell dysfunction in response to glucose levels." (PMID 26350756, 2015). "In fact, patients with type 2 diabetes under insulin therapy typically measure glycemia preprandially, before insulin administration, and possibly at bedtime." (PMID 26587020, 2015). "Insulin analogues have been dispensed to both type 1 and type 2 diabetes patients for the last 10 years by the State Health Secretariat of the Federal District (SHS-FD) in Brazil." (PMID 26288660, 2015). "Patients with type 2 diabetes generally suffer both from reduced insulin secretion and from resistance to the actions of insulin." (PMID 26490765, 2015). "This randomized, controlled study was initiated owing to the scarcity of data regarding PROs after BOT initiation with insulin glargine or NPH insulin in type 2 diabetes patients." (PMID 26055391, 2015). "Among the synthetic ligands that selectively activate PPAR-γ, thiazolidinedione is an insulin sensitizer that is used to treat hyperglycemia in type 2 diabetes." (PMID 26408008, 2015). "Many patients with type 2 diabetes struggle to achieve adequate glucose control despite escalation of therapy including complex insulin regimens with multiple daily injections (MDIs)." (PMID 29632572, 2015). "That said, to give more concrete content to the wide-ranging discussion on the type 2 diabetes pathophysiology, we propose to replace the word-combination ‘insulin resistance’ by ‘reduced membrane flexibility’." (PMID 27123439, 2015). "An insufficiency in functional β-cell mass and their aptitude to secrete insulin is a characteristic feature of type 2 diabetes." (PMID 26568772, 2015). "Among those with type 2 diabetes, the mean basal insulin dose was higher with detemir (74 vs. 56 units/day, p < 0.01)." (PMID 26120575, 2015).
type 2 diabetes (continued). "Chemically synthesized PPAR-γ agonists, such as thiazolidines, can selectively activate PPAR-γ to increase the peripheral sensitivity to insulin and reduce the blood glucose level and are commonly used to treat type 2 diabetes." (PMID 26516376, 2015). "Type 2 diabetes mellitus (T2DM) is a progressive multifactorial, complex group of metabolic disorders characterized by hyperglycemia owing to impaired insulin sensitivity and/or insulin deficiency." (PMID 25838947, 2015). "In humans, one clinical trial demonstrated an association between the low dietary consumption of AGEs and improvement in insulin sensitivity in patients with type 2 diabetes." (PMID 26223897, 2015). "Oral administration of the GD-lyophilized powder has been effectively hypoglycemic, which is done by activating insulin signaling and improving antioxidant capacity in mice with type 2 diabetes." (PMID 26715102, 2015). "To date, there have been no human trials investigating the impact of a dietary AGE intervention on direct measures of insulin sensitivity and insulin secretion or on the development of type 2 diabetes." (PMID 26223897, 2015). "Improvements due to PA in type 2 diabetes include increased insulin sensitivity and responsiveness along with a positive effect on lipids, blood pressure, cardiovascular events, mortality and quality of life." (PMID 26468874, 2015). "Our findings were similar to that of a recent study by Bryant and colleagues (2013), which examined 31 patients with type 1 or type 2 diabetes who converted from insulin glargine to insulin detemir after a Medicaid formulary switch." (PMID 26120575, 2015). "Hypoglycemia-associated autonomic failure (HAAF), which is characterized by defective glucose counterregulation during hypoglycemia, is a well-known neuroendocrine complication in children and adults on insulin therapy for type 1 and type 2 diabetes." (PMID 26343738, 2015). "Upregulated canonical pathways included those related to adipocytokine, insulin, and type 2 diabetes signaling (e.g., Adipor1, Prkab1, and Acacb)." (PMID 25744495, 2015). "Insulin is the most common treatment in type 1 diabetes (T1D) patients, while most patients with type 2 diabetes (T2D) receive oral treatments although many are treated with insulin." (PMID 29632571, 2015). "Genome-wide and tissue specific deletion of PTP1B increases insulin sensitivity and confers protection against obesity and type II diabetes in mice." (PMID 25974252, 2015). "Our results are also consistent with the finding of elevated betatrophin in patients with obesity and type 2 diabetes, however unchanged or even decreased serum betatrophin levels have been reported in diabetic or/and insulin resistant patients as well." (PMID 26115519, 2015). "Impaired insulin secretion is a major pathophysiological disturbance in type 2 diabetes, and hyperglycemia further impairs β-cell function." (PMID 25853252, 2015). "Diabetes type 2 is a state which presents with different degrees of resistance to insulin and glucose production." (PMID 25848640, 2015). "After a longer period of time, the pancreas fails in meeting insulin needs after meals, leading to impaired glucose tolerance, and finally to type 2 diabetes." (PMID 27417770, 2015). "The developed cellular imaging assay provides a unique platform for the understanding of inflammation and insulin resistance signaling pathways in type II diabetes mellitus and how they regulate each other." (PMID 25623542, 2015). "Individuals with type 2 diabetes usually have an excess of insulin, and those with worse glucose control have the highest serum levels [24••]." (PMID 25648962, 2015). "In this study, we evaluated the efficacy of vildagliptin administered at the dose of 100 mg twice daily in 57 patients with type 2 diabetes already receiving insulin treatment." (PMID 25780477, 2015). "In patients with type 2 diabetes from the same organization, we previously found insulin use is a predictor of requesting a login." (PMID 26086272, 2015).
type 2 diabetes (continued). "In randomized controlled clinical trials a 6-week supplementation of one of the most promising fibers (guar gum) reduced fasting plasma glucose and insulin levels, and increased insulin sensitivity in healthy and type 2 diabetes humans." (PMID 26292284, 2015). "GLP-1 and GIP contribute to approximately 60–70% of the total postprandial insulin response in healthy individuals, and have a potentially therapeutic value in the treatment of type II diabetes." (PMID 26222180, 2015). "In animal models of type-2 diabetes these complexes have shown a significant ability to reduce blood glucose, HbA1c, serum insulin, triglycerides and total cholesterol, whilst improving glucose tolerance." (PMID 26381880, 2015). "Structured physical exercise is well‐known to have positive effects on insulin sensitivity and glucose control in healthy adults as well as those with type 2 diabetes." (PMID 26660554, 2015). "The thiazolidinedione (TZD), pioglitazone, remains a mainstay of insulin sensitizing therapeutics for the management of type 2 diabetes." (PMID 25954816, 2015). "In skeletal muscles, the liver, and adipose tissues, activation of AMPK can increase metabolism, insulin sensitivity, and gene expression, and all of these effects are beneficial in preventing type 2 diabetes." (PMID 25768846, 2015). "Insulin is glycated even in the pancreas which has been considered in the pancreas of various animal models of type 2 diabetes." (PMID 26311627, 2015). "This study demonstrates that the initiation of insulin in patients with type 2 diabetes in clinical practice leads to increased health care contacts, overall and treatment costs, but also generally results in a decrease in health care costs." (PMID 28702235, 2015). "It was reported that low levels of 12α-hydroxylated BAs appear to link hepatic insulin signaling in type 2 diabetes with dyslipidemia." (PMID 26372644, 2015). "Liraglutide also increases both first and second phases of insulin secretion in type 2 diabetic patients." (PMID 25938469, 2015). "People with Type-1 or insulin-treated Type-2 diabetes > 15 years of age completed up to 4 questionnaires (weekly intervals)." (PMID 25421366, 2015). "Metformin, a well-known insulin-sensitizer commonly used for type 2 diabetes therapy that is gaining attention in cancer research, has recently been found to inhibit growth and sensitize osteosarcoma cell lines to cisplatin." (PMID 25999349, 2015). "Clinically, type 2 diabetes is evidenced by a rise in blood glucose due to faulty insulin-dependent signaling mechanisms." (PMID 26336514, 2015). "These included genes involved in starch and sugar metabolism, in the insulin signaling pathway, and in type I and type II diabetes mellitus." (PMID 26490036, 2015). "Previous studies have demonstrated that insulin-stimulated PI3K activity decreases in the skeletal muscles of patients with type II diabetes." (PMID 25352008, 2015). "Current evidence shows hypoglycaemia is considerably prevalent amongst people with type 2 diabetes, particularly for those on insulin, yet still fairly common for other treatment regimens." (PMID 26061690, 2015). "In preclinical type 2 diabetes, beta cells secrete excessive insulin and considerably expand their mass to compensate for the increased metabolic load and obesity-associated insulin resistance." (PMID 25658116, 2015). "Taken together, these results suggest that intranasal delivery of GNP holds promise as a future rescue medication for use by caregivers to treat insulin-induced hypoglycemic episodes in patients with type 1 or type 2 diabetes." (PMID 26502880, 2015). "Skeletal muscles have a primarily important role in maintaining normal glucose homeostasis, and type 2 diabetes is characterized by insulin resistance in skeletal muscles." (PMID 25768846, 2015). "ROS is believed to promote the onset of type II diabetes by decreasing insulin sensitivity and damaging insulin-producing β-cells in the pancreas." (PMID 26132844, 2015).